SUPT20HL1 (SUPT20H like 1)
Synonyms: FAM48B1; SPT20L
Gene: Protein-coding gene on chromosome X (24,360,639 to 24,367,839, forward strand). Ensembl gene ENSG00000223731.
Homologues: Orthologues: chimpanzee SUPT20HL1 (91% identical), tropical clawed frog supt20h (42% identical), zebrafish supt20 (41% identical), rat Supt20hl2 (36% identical), mouse Gm61616 (35% identical), mouse Gm61617 (31% identical), Drosophila melanogaster Spt20 (27% identical), rat Supt20hl1 (20% identical). Paralogues in human: SUPT20HL2 (85% identical), SUPT20H (50% identical).
Diseases named in the same sentence as SUPT20HL1 in open-access papers:
SUPT20HL1 is named in the same sentence as 2 diseases in open-access papers, as found by Europe PMC text mining. Sharing a sentence is not in itself a finding about the gene and the disease.
SUPT20HL1 shares sentences with these, for which no sentence is quoted: cancer (1 paper); ovarian carcinoma (1).